SACS (sacsin molecular chaperone)
Description:
Co-chaperone which acts as a regulator of the Hsp70 chaperone machinery and may be involved in the processing of other ataxia-linked proteins.
Synonyms: DNAJC29; KIAA0730; ARSACS; DKFZp686B15167; SPAX6; PPP1R138
Tractability: PROTAC: ubiquitination databases record sites on it; its protein half-life has been measured.
Gene: Protein-coding gene on chromosome 13 (23,288,689 to 23,433,763, reverse strand). Ensembl gene ENSG00000151835.
Subcellular location: Cytoplasm
Gene Ontology:
Molecular function: Hsp70 protein binding; identical protein binding; low-density lipoprotein particle receptor binding; proteasome binding; protein-folding chaperone binding
Biological process: negative regulation of inclusion body assembly; protein folding
Cellular component: cytoplasm; mitochondrion; nucleus; axon; cell body fiber; dendrite
Genetic constraint (gnomAD): Loss-of-function variants: 193 observed, 337.62 expected, observed/expected ratio (o/e) 0.57, 90% interval 0.51 to 0.64. The upper end of that interval is the gene's LOEUF score, 0.64, which puts it in group 2 of 6, group 1 being the genes least tolerant of losing a copy. Missense variants: 4,879 observed, 5,492.7 expected, observed/expected ratio (o/e) 0.89, 90% interval 0.87 to 0.91. Synonymous variants: 1,927 observed, 1,968.9 expected, observed/expected ratio (o/e) 0.98, 90% interval 0.94 to 1.02.
Homologues: Orthologues: chimpanzee SACS (99% identical), macaque SACS (99% identical), rabbit SACS (96% identical), dog SACS (96% identical), mouse Sacs (94% identical), rat Sacs (94% identical), guinea pig SACS (93% identical), pig SACS (91% identical), tropical clawed frog sacs (78% identical), zebrafish sacs (70% identical).